MAGEA3 (MAGE family member A3)
Diseases named in the same sentence as MAGEA3 in open-access papers (continued):
Sharing a sentence is not in itself a finding about the gene and the disease.
tumor (269 papers, 2001 to 2026). "When examining the similarities between the Phase III trials MAGRIT, START, START2, and TIME, only one tumor antigen was encoded in each vaccine (MAGEA3 for MAGRIT, and MUC1 for START, START2, and TIME)." (PMID 41542091, 2025). "It is associated with the products of tumor-associated gene as autoantibodies (aTAAs) in reaction to the tumor-associated antigens (TAAs), with increasing of anti-MAGEA3 and an relationship between the abscopal effect and immune response." (PMID 37336938, 2023). "We also noticed increased expression of the EMT activator ZEB1, the tumor-associated antigens MAGEA3/A6 and MAGEC2, and metalloproteinase in EMThi cancer cells." (PMID 35503263, 2022). "Taken together, inhibition of MAGEA3 led to a significant increase in apoptosis via loss of Survivin, further suggesting the role of MAGEA3 in tumor progression." (PMID 34166362, 2021). "When MAGEA3 protein was used as an ELISA diagnostic antigen, it can be recognized by tumor that expressed MAGEA3." (PMID 34970496, 2021). "After adjustment by tumor purity, the analysis showed that the expression of MAGEA3 was significantly associated with most of the marker of immune cells in GC." (PMID 34970496, 2021). "The expression of tumor-associated genes like PTK7 and MAGEA3 escalated, implying a potential increase in metabolic activities and nuclear functions during cellular transformation, correlating with elevated proliferation and enhanced viability in tumor cells." (PMID 38720887, 2024). "Furthermore, the protein expression of MAGEA3 correlated with stage and tumor biomarker NSE, and the diagnostic efficacy of MAGEA3 serum protein is better than that of serum." (PMID 38555374, 2024). "As a proof of principle for CrossDome, we used the tumor-associated peptide from MAGEA3 (EVDPIGHLY) as a query, and evaluated the capacity of our method to recover the known cross-reactive peptide derived from TITIN (ESDPIVAQY) among the top-ranked putative off-targets." (PMID 37377956, 2023). "Indeed, previous work has shown MAGEA3 can alter tumor immune microenvironment and associate with immune infiltrates, suggesting it may promote immune tolerance." (PMID 41452900, 2025). "These included MAGEA3, MAGEA6 and MAGEA10, all cancer‐testis antigens previously associated with higher tumour grade, stage, and risk of invasion in NMIBC." (PMID 41425537, 2025). "While MAGEA3 and MUC1 have been established as immunogenic tumor antigens capable of generating anti-tumor T cell responses, it is possible that encoding only one tumor antigen in a lung cancer vaccine formulation is not sufficient to broadly prolong survival." (PMID 41542091, 2025). "In our AOM/DSS model, we found that MAGEA3 expression in peri-tumor colon tissue of AOM/DSS-treated mice was significantly higher than in colon tissue of untreated mice, further supporting the role of MAGEA3 in tumorigenesis." (PMID 40342736, 2025). "Our results showed that the mRNA level of MAGEA3 in tumor and peri-tumor colon tissues from AOM/DSS-treated mice was significantly higher compared to normal colon tissues of untreated mice." (PMID 40342736, 2025). "Results showed that the MAGEA3 protein level was higher in tumor tissue than in peri-tumor tissue in human CRC." (PMID 40342736, 2025). "It should be noted that MAGEA3 is only expressed in tumor cells, while VEGF can also be expressed by other stromal cells in cancer." (PMID 40342736, 2025). "Because of the tumor-specific expression patterns and pro-tumorigenic functions of MAGEA3, immunotherapy and targeted therapy have been explored in previous studies." (PMID 40342736, 2025). "Further, we used Western blot to detect the MAGEA3 protein level in AOM/DSS mouse models, which showed elevated protein level of MAGEA3 in the peri-tumor tissues and further elevation in the tumor tissues in AOM/DSS-treated mice compared to untreated mice." (PMID 40342736, 2025).
tumor (continued). "Based on RNA-seq data from TCGA-STAD, tumor tissues exhibited significantly elevated MAGEA3 and MAGEA6 expression compared to normal tissues." (PMID 41452900, 2025). "Previous studies have shown that MAGEA3 plays diverse roles in tumor cell proliferation and apoptosis, and interacts with several signaling pathways." (PMID 40342736, 2025). "MAGEA3 mRNA associated with tumor diameter, TMN stage, and NSE in LUAD serum samples, and MAGEA3 mRNA correlated with N stage in serum-derived exosomes, possessing areas under the curve (AUC) of 0.721 and 0.832, respectively." (PMID 38555374, 2024). "Post-treatment tumors also exhibited a significant downregulation of tumor antigens (MAGEA3, BST2) when compared to baseline." (PMID 39506856, 2024). "MAGEA3 immunogenicity and carcinogenicity ranked eighth out of 75 tumor antigens in a National Cancer Institute study and ranked first in CTAs14." (PMID 38555374, 2024). "MAGEA3, which was expressed in all cells including tumor cells, is a Cancer Testis Antigen (CTA) and reported in almost all types of cancer and is considered a promising candidate for immunotherapy." (PMID 38962317, 2024). "Macrophages M2, a cancer-promoting phenotype of macrophages, was positive correlated with MAGEA3, which indicated that with the increase of MAGEA3, it contributes to the formation of tumor microenvironment promoting cancer." (PMID 38555374, 2024). "To investigate this, we studied the ability of γδ T-APCs to cross-present MAGEA3, a cancer–testis antigen that has been widely used in clinical trials for tumor vaccines." (PMID 36680568, 2023). "For instance, MAGEA3 overexpression has been shown to increase tumor growth and metastasis, while silencing MAGEA3 inhibits cancer cell proliferation." (PMID 37814317, 2023). "Individually, MAGEA1, MAGEA3, MAGEA4, MAGEC2 and NY-ESO-1 are highly expressed in HCC and associated with metastasis, tumor recurrence, high AFP levels and poor clinical outcomes." (PMID 34166362, 2021). "We first discovered that MAGEA3 was elevated in tumor tissues, which was significantly correlated with poor OS." (PMID 34970496, 2021). "Many clinical trials with this antigen also have been carried out, which include being vaccinated with a strictly tumor-specific MAGEA3 peptide or MAGEA3 protein." (PMID 34970496, 2021). "Experimental evidence in vitro and in vivo identifies the role of the XCTA MAGEA3 in tumor progression through apoptosis inhibition by Survivin upregulation, which underscores the role of MAGEA3 as a novel therapeutic target in HCC." (PMID 34166362, 2021). "Here we present a comprehensive analysis of XCTA gene family expression in HCC and describe the active role of MAGEA3 in promoting tumor progression." (PMID 34166362, 2021). "To establish a mechanism by which MAGEA3 drives tumor progression in HCC, we performed RNA sequencing on the PLC5 cell line after knockdown with sh8375." (PMID 34166362, 2021). "This study adds data to a growing field of evidence in support of MAGEA3 as a driver of tumor progression and a potential novel therapeutic target in human cancer." (PMID 34166362, 2021). "Since MAGEA3 is abnormally highly expressed in tumor sample, we subsequently investigated the influence of MAGEA3 expression on GC patients’ prognosis and clinicopathology." (PMID 34970496, 2021). "a-c Digital images (a, scale bar 1 cm) of xenografts isolated from nude mice and graph (b, tumor volume and c, tumor weight) showing greater size and weight of tumors generated from BxPC3 cells overexpressing MAGEA3 constitutively." (PMID 31287009, 2019). "The in vivo xenograft study revealed that overexpression of MAGEA3 promoted tumor growth however depleting the same hindered the tumor progression." (PMID 31287009, 2019).
tumor (continued). "The immunohistochemical analysis of tumor samples from BxPC3 xenografts showed enhanced BrdU and survivin positive cells upon MAGEA3 overexpression but was lowered in MAGEA3 depleted xenografts (BxPC3-sh1) compared to control tumors." (PMID 31287009, 2019). "We also dissected the mechanism behind the MAGEA3 role in tumor progression using western blot analysis and CCL2 neutralization." (PMID 31287009, 2019). "The MAGEA3 overexpressing or depleted stable PCCs were evaluated in vivo using xenograft model to check the role of MAGEA3 in tumor progression." (PMID 31287009, 2019). "Mechanistically, our in vitro and in vivo study revealed that MAGEA3 has tumor-promoting role by reducing macro-autophagy and overexpressing pro-survival molecules like CCL2 and survivin." (PMID 31287009, 2019). "The tumor-promoting role of MAGEA3 was assessed firstly by in vitro cell proliferation assay in complete growth medium (10% FBS)." (PMID 31287009, 2019). "Estimation of tumor weights showed a significantly higher tumor weight of MAGEA3 overexpressing tumors than controls." (PMID 31287009, 2019). "d-f Digital images (d, scale bar 1 cm) of tumors dissected from nude mice and graph (e, tumor volume and f, tumor weight) showing reduced tumor size and weight upon MAGEA3 knockdown." (PMID 31287009, 2019). "It has been reported that MAGEA3 is expressed in a sporadic pattern in tumor tissues, which limits the strategy of immunotherapy using MAGEA3 as a candidate." (PMID 31287009, 2019). "Our analysis of large, publicly available tumor (Cancer Genome Atlas) and cancer cell line (Cancer Cell Line Encyclopedia) databases shows that MAGEA3 is expressed in UPS/MFS." (PMID 31096717, 2019). "The effects of DAC on MAGEA-1, MAGEA-3, and p16 expressions in blood samples and cell lines are consistent with the results of previous studies of a variety of other tumor types." (PMID 24963497, 2014). "In the future, experiments with tumor relevant antigens like MageA3, Trp2, p62 and brachyury, have to confirm the observed results with the egg white derived protein ovalbumin." (PMID 24519916, 2014). "In contrast, our results suggest the CD4+ T cells to be critical effectors in this MAGEA3-transfected tumor model." (PMID 24830315, 2014). "Other cases have been reported, including a case of a man with brain metastases and nodal metastases who had a CR to concurrent treatment with ipilimumab and SRS and developed antibodies to the tumor antigens MAGEA3 and PASD1." (PMID 24403263, 2013). "Significant tumor-specific demethylation was found in MAGEA3 (p<0.005), MAGEA12 (p<0.025), MAGEA4 (p<0.018), MAGEA1 (p<0.001), TKTL1 (p<0.025) and MAGEA5 (p<0.007)." (PMID 19997593, 2009). "Additionally, the high expression of MAGEA3 enables tumor cells to exhibit lower mitochondrial metabolism." (PMID 40342736, 2025). "Additionally, tumor-associated antigens such as MAGEA1, MAGEA3, and GTAp63 were also induced by Chidamide, promoting antigen presentation and T-cell recognition (data not shown)." (PMID 41049003, 2025). "MAGEA3 has varying effects on the phenotype of different tumor cells." (PMID 40342736, 2025). "Genes involving the extracellular space and plasma membrane regulators were increased in aggressive MSI‐H CRC tumors, and tumor antigens (MAGEA3, MAGEA6, MAGEA9B, or MAGEC2) involving in the transcriptional and post‐translational regulations were represented in the aggressive MSI‐H signature." (PMID 39322998, 2025). "This negative correlation between the expression level of MAGEA3 and central CD4 + T cells, CD8 + T cells and Th17 cells using TISIDB database.These results indicated that MAGEA3 might have an important effect on tumor immune infiltration in LUAD." (PMID 38555374, 2024). "Furthermore, MAGEA3 had significant differences in the clinical stage and traditional tumor biomarker NSE." (PMID 38555374, 2024).
tumor (continued). "In addition, tumours with high TMI show enrichment for Mage family member A3 (MAGEA3) and CD8 positive T cells and also display high expression of B7-H3 which is negatively associated with clinical outcome in solid tumours." (PMID 36190948, 2022). "Additionally, since the TCGA-LIHC and Heptromic cohorts are composed of single biopsies samples, we cannot observe the intra-tumor heterogeneity of MAGEA3 expression in these patients." (PMID 34166362, 2021). "Many research have reported the abnormal expression of MAGEA3 in many tumor types." (PMID 34970496, 2021). "Interestingly, differential expression analysis of whole proteomes comparing the two groups (TMIhigh vs. TMIlow) identified MAGEA3, a frequently expressed tumor-specific antigen, as the second most highly expressed protein in TMIlow tumors." (PMID 31123708, 2019). "Interestingly, overexpression of MAGEA3 in MAGEA3 positive cell line BxPC3 further enhanced the tumor progression in vivo." (PMID 31287009, 2019). "g, h Immunoblot and PCR showing MAGEA3 level in the tumor samples." (PMID 31287009, 2019). "In our study, the presence of more number of cancer cells in MAGEA3 overexpressing tumors might be due to better survival and/or proliferation of cancer cells in tumor tissues." (PMID 31287009, 2019). "The tumor promoting role of MAGEA3 was further examined in MAGEA3 positive cell line." (PMID 31287009, 2019). "Our data proves tumor-promoting role of MAGEA3 and provides the rationale to target MAGEA3 and/or its functional mediators like CCL2 for PCA, which may have a better impact in PCA therapy." (PMID 31287009, 2019). "Based upon our initial evaluation of CTA gene induction with HMAs, we elected to further examine induced NY-ESO-1 and MAGEA3/A6 expression in a larger cohort of AML patients as these genes are established tumor antigens with clinically translatable vaccines in development." (PMID 26883197, 2016). "Enhanced expression of MAGEA-1 and MAGEA-3 on the surfaces of malignant cells might lead to more effective “killing” of the tumor cells by cytotoxic T-cell-receptor-based immunotherapeutics." (PMID 24963497, 2014). "Therefore, we further explored the relationship between MAGEA3 and tumor immune cell infiltration." (PMID 38555374, 2024). "Therefore, OVs already encoding tumor antigens such as the clinical candidates Ad-MAGEA3 and MRB-MAGEA3 or Ad-E6/E7 and MRB-E6/E7 could easily be used as vaccination adjuvants to target additional Muts in MAGEA3- or E6/E7-positive tumors, respectively." (PMID 33976179, 2021). "However, the tumor progression was hindered when MAGEA3 was knocked down in BxPC3 cell line." (PMID 31287009, 2019). "However, in the in vivo context, in addition to this direct effect, MAGEA3 might have also indirectly affected the overall tumor growth by modulating different stromal events like angiogenesis." (PMID 31287009, 2019). "Strong anti-tumor reactivity of the CTA-specific TCR T cells against different tumor cell lines correlated with markedly induced expression of MAGEA1, MAGEA3/A6, and MAGEA9 by DAC treatment." (PMID 40791813, 2025). "MAGEA3 expression is detected in over 30% of NSCLC patients, positively correlating with smoking status, advanced tumor stage, and poor outcome." (PMID 41542091, 2025). "For MAGEA3/A6, gene expression was induced to 1% of HKG for healthy B cells and T cells and around 0.1% for fibroblasts, which was generally lower than in tumor cells with a mean relative expression level of ∼30% HKG expression." (PMID 40791813, 2025). "DAC treatment of tumor cells again resulted in the induction of MAGEA1, MAGEA3/MAGEA6, or MAGEA9 expression as validated by qPCR." (PMID 40791813, 2025).
tumor (continued). "In summary, DAC treatment can substantially induce or enhance the reactivity of MAGEA1-, MAGEA3/A6-, and MAGEA9-specific TCR T cells toward diverse tumor cell lines." (PMID 40791813, 2025). "The clinicopathological feature shed light into a solid relationship between MAGEA3 and TNM classification, stage and tumor diameter (P < 0.05)." (PMID 38555374, 2024). "To test this, we developed a MAGEA3 and MYC overexpression transposon vector (pT3-EF1a-Myc-Ires-MAGEA3) to compare the rate of tumor development against the MYC transposon vector alone." (PMID 34166362, 2021). "MAGEA3 was also correlated with immune checkpoints, TMB, and affected the tumor immune microenvironment and the prognosis of GC through CIBERSORT, TIMER, and Kaplan-Meier plotter database analysis." (PMID 34970496, 2021). "Known HCC drivers such as LIN28B and candidate driver genes, including a sub-set of CTAs (i.e., MAGEA3, MAGEA1), were significantly upregulated (>10 FC, FDR<0.001) in high grade regions compared to low-grade regions of the same tumor nodule." (PMID 34166362, 2021). "Another important observation was that the amount of tumor-specific EVs (enriched using tumor-specific markers anti-EGFR, anti-MAGEA3, anti-EpCAM, and anti-CSPG-4) varied among different patients." (PMID 33158181, 2020). "We observed significant upregulation of both New York-Esophageal Cancer-1 (NY-ESO-1) and Melanoma Antigen Family A3/6 (MAGEA3/A6), established immunogenic tumor antigens." (PMID 26883197, 2016). "When the Wilcoxon signed-rank test was used, we noted that 6 of 18 (33%) CTAs tested, MAGEA3, OIP5, TTK, PLU1, DKKL1, and FBXO39, were significantly (p < 0.05) overexpressed in the tumor compared with normal tissue located ~5 cm away from the primary lesion." (PMID 27635108, 2016). "Previous studies have also shown that MAGEA3 can regulate the ubiquitination degradation of AMPK, as well as activate the mTOR pathway and inhibit the autophagy pathway, which can also impact the metabolic status of tumor cells." (PMID 40342736, 2025). "In addition, in the TCGA database, both MAGEA3 and ANGPT2 were found to be significantly overexpressed in tumor tissues compared to normal tissues." (PMID 40342736, 2025). "Additionally, the expression of MAGEA3 and MAGEA6 was higher in tumor tissues compared to adjacent normal tissues." (PMID 41452900, 2025). "With the exception of MAGEA3 that showed a barely significant P-value (P = 0.05), no other conserved tumor antigen reached significance." (PMID 36909826, 2023). "We hypothesized that if MAGEA3 plays an active role in HCC progression, the additional overexpression of MAGEA3 in this model would lead to accelerated tumor development." (PMID 34166362, 2021). "In conclusion MAGEA3 enhances tumor progression and should be considered as a novel therapeutic target in HCC." (PMID 34166362, 2021). "There is no single gene that was significantly more expressed in tumor tissue, with the exception of the cancer testis gene MAGEA3." (PMID 30016964, 2018). "More surprising was the observation that CD8+ T cells do not seem to be essential in this MAGEA3-transfected tumor model, as demonstrated in CD8+ T cell-depleted mice or perforin-KO mice." (PMID 24830315, 2014). "The epigenetic reactivation of TKTL1, H19, MAGEA2, MAGEA3/6, MAGEA4, MAGEA11, GPR17, GRIN1, and C19ORF28, genes located at diverse chromosomal loci, occurs simultaneously in individual primary tumors from multiple tumor types." (PMID 19305507, 2009). "However, tumor cells can aberrantly upregulate MAGEA3 in non-immune privileged tissues, triggering an anti-tumor immune response." (PMID 41542091, 2025). "To assess whether MAGE genes were induced to levels that could be relevant for T-cell-mediated recognition, we compared the relative expression levels of MAGEA1, MAGEA3/MAGEA6, and MAGEA9 after DAC induction in healthy cells to the relative expression levels in tumor cells." (PMID 40791813, 2025).